GDNF (glial cell derived neurotrophic factor)
Diseases named in the same sentence as GDNF in open-access papers (continued):
Sharing a sentence is not in itself a finding about the gene and the disease.
cancer (continued). "Cancer cell invasion of the DRG was partially dependent on DRG secretion of glial-derived neurotrophic factor (GDNF)." (PMID 22768171, 2012). "In migration assays, single fraction radiation of MiaPaCa2 inhibited cancer cell migration towards GDNF and DRG in a dose-dependent fashion." (PMID 22768171, 2012). "Previous studies showed that overexpression of c-RET, GFRa1 and/or GDNF indicated poor prognosis in human pancreatic and bile duct carcinomas." (PMID 20422010, 2010). "GDNF, a neurotrophic factor secreted by damaged nerves or glial cells, can activate the GFRα cognate tyrosine kinase receptor, thereby stimulating the directional migration and invasion of cancer cells." (PMID 41556039, 2026). "Notably, 29 genes, including APOBEC2, GDNF, and PRELP, have been confirmed by existing literature to be associated with cancer development and progression." (PMID 39968416, 2025). "It was demonstrated that GDNF can induce the migration of HPV-positive SCC cancer cells." (PMID 39906323, 2024). "In-vitro co-culture of dorsal root ganglia and human pancreatic adenocarcinoma cell lines and in-vivo murine sciatic nerve models of PNI showed that nerves release GDNF, and induce polarized neurotrophic migration of cancer cells via downstream pathways of RET." (PMID 35223829, 2022). "However, a conclusion emerging from our studies is that GDNF-RET signalling in MNs is more complex than in cancer cell lines." (PMID 35798698, 2022). "GDNF has been well studied in other cancers and found to promote migration and invasion." (PMID 33628594, 2021). "Treatment with regorafenib (RET inhibitor) reduced cancer invasion along neurites, suggesting that GDNF may have a critical role in PNI in head and neck SCC." (PMID 34885121, 2021). "In addition, GDNF is also abnormally expressed in other malignant tumors such as pancreatic, breast, and prostate cancers, which promotes invasive tumor cell growth." (PMID 32183903, 2020). "Cancer cell migration induced by macrophage-derived GDNF depends on GFRα1 co-receptor and RET, as demonstrated by the inhibitory effect observed in knock down experiments with cells lacking GFRα1 co-receptor and the use of RET inhibitor (pyrazolopyrimidine-1, PYP1)." (PMID 32555170, 2020). "During tumorigenesis, cancer cells secrete Colony Stimulating Factor (CSF–1) to recruit macrophages; in turn, recruited macrophages release glial derived neurotrophic factor (GDNF) that activates RET (REarranged during Transfection) on cancer cells to promote cancer migration and nerve invasion." (PMID 31248001, 2019). "GDNF has been demonstrated to induce cancer cells migration." (PMID 29334991, 2018). "Our studies demonstrated that high glucose in vitro might be regarded as an accelerator to increase cancer cell proliferation by enhancing the glial cell line-derived neurotrophic factor (GDNF)/RET or epidermal growth factor (EGF)/EGFR signaling pathways." (PMID 30455857, 2018). "Furthermore, GDNF were found to be overexpressed in cancer cells that were resistant to the anti-angiogenic treatment using the VEGF antibody." (PMID 27167204, 2016). "DNA hypermethylation contributes to the low expression of GDNF in several human cancers." (PMID 24564330, 2013). "We demonstrate that a single dose of radiation may impair PNI through not only cancer cell death, but also independent effects on the nerve itself and the nerve's production of GDNF, a potent chemotactic factor." (PMID 22768171, 2012). "In addition, several of the promoter-hypermethylated genes were associated with the development of human cancers and these include GIPC2, DIRAS3, TYSPL6, EDNRB, FYN, GDNF, RASSF1, and RASSF2." (PMID 21962230, 2011).
cancer (continued). "In our previous study, cancer‐derived exosomes carrying XIST may activate neurons to secrete GDNF." (PMID 40985319, 2025). "However, because neurotrophic factors have been reported to play a potential role in cancer aggressiveness, we performed a systematic preclinical and clinical evaluation of the effect of GDNF in HNSCC through the use of several different cell lines and patient cohorts." (PMID 32084217, 2020). "Conversely, neural structures release factors such as NGF, GDNF, ARTN, and CXCL12 (SDF-1), which act as chemoattractants for cancer cells expressing corresponding receptors." (PMID 40909268, 2025). "It has also been reported that HNSCC cancer cells can secrete neurotrophins and neurotransmitters such as NGF and GDNF." (PMID 38525111, 2024). "Recent studies have shown that cancer cells express neurotrophic markers such as NGF, BDNF, and GDNF and release axon guidance molecules such as Ephrin B1 to promote axonogenesis, neurogenesis, and neuronal reprogramming." (PMID 38920662, 2024). "Activated endoneurial macrophages secreted high levels of GDNF, promote RET phosphorylation on PDAC cell membrane, activated downstream MAPK and PI3K pathways in cancer cells, and enhance PNI." (PMID 39119085, 2024). "This idea is supported by the upregulation of neuronal receptors such as AMAPR, NMDAR, GFRα1, GFRα2, GFRα3, AChR, L1-CAM, and NCAM and their ligands, including glutamine, GDNF, NRTN, ARTN, and Ach, in cancers." (PMID 37566075, 2023). "GFRA2 and GFRA3 were glial cell line-derived neurotrophic factor (GDNF) receptors, and previous studies have suggested their participation in cancer." (PMID 35646712, 2022). "Changes in DRD3 levels along with GDNF, GNAL, HRH2, CAV2, and DLG4 were characteristic of G1 cancer." (PMID 34768458, 2021). "Artemin activates the glial cell-derived neurotrophic factor (GDNF) family receptor alpha-3 (GFRα3) and its co-receptor RET on cancer cells." (PMID 33669537, 2021). "Cancer cells secrete factors such as NGF, ARTN, CXCL12/SDF-1 which attract Schwann cells, and Schwann cells secrete GDNF, TGF-β and provide NCAM-1-mediated cell-cell interaction to promote cancer cell migration and aggressiveness." (PMID 33050151, 2020). "Of note, GDNF secreted by M2 polarized recruited–perineurial macrophages, activates RET on cancer cells promoting PNI." (PMID 31248001, 2019). "PNI is influenced by the interaction between the nerve microenvironment and neurotrophic molecules expressed by cancer cells such as nerve growth factor (NGF), BDNF, glial cell line-derived neurotrophic factor (GDNF) and their receptors." (PMID 29334991, 2018). "In addition to NGF and GDNF, BDNF increases cancer cell invasion and chemotaxis toward nerves through TrkB‐mediated activation of phosphoinositide 3‐kinase (PI3K)/AKT and mitogen‐activated protein kinase (MAPK)/ERK signaling pathways." (PMID 41556039, 2026). "Chemokines such as CCL2, or endocrine hormones and neurotrophic factors, including nerve growth factor (NGF) and glial-derived neurotrophic factor (GDNF), are known to promote both in vitro and ex vivo culture models, suggesting that cancer cells surrounding nerves exhibit increased survival." (PMID 40427098, 2025). "Notably, MONet identified 37 novel driver genes that were missed by other methods, including 29 genes such as APOBEC2, GDNF, and PRELP, which are corroborated by existing literature, underscoring their critical roles in cancer development and progression." (PMID 39968416, 2025). "GDNF molecules promote survival, proliferation, migration, and invasion through effectors such as MAP kinase, AP-1 transcription factor, and MMPs in various cancer cell types." (PMID 39906323, 2024). "Besides, soluble GFRα1 released from the DRG cells after binding with the cancer-derived GDNF activates the MAPK pathway, resulting in cells’ enhanced migratory potential and, in effect, nerve invasion by the cancer cells." (PMID 39906323, 2024).
cancer (continued). "Since several studies have reported that RET activates STAT3 in different types of cancer, CDK5-mediated STAT3 activation with GDNF treatment remains unknown in this study." (PMID 34207842, 2021). "In human pancreatic adenocarcinoma (MiaPaCa-2) cells, GDNF binds to its receptor GFRalpha1, activates the RET co-receptor, and promotes mitogen-activated protein kinase (MAPK) signaling to induce cancer cell migration towards nerve in vitro and animal models of PNI." (PMID 34885121, 2021). "GDNF is a potent neurotrophic factor with demonstrated ability to induce migration of non-neuronal cells, including cancer cells." (PMID 32084217, 2020). "Similarly, Glial cell line–Derived Neurotropic Factor (GDNF) and artemin (ARTN), released by cancer, increase TRPV1 expression and thus pain sensibility." (PMID 31248001, 2019). "Moreover, targeting the GDNF–RET axis as well as LIF inhibition reduces PNI both in vitro and in vivo, while targeting Neurturin impairs PNI and cancer aggressiveness." (PMID 31248001, 2019). "BT13 is a short-living compound having lower efficacy than GDNF (for example its activated luciferase in screening assay by maximum 11.6 fold, whereas GDNF—by 50–100 folds, thus, it is unlikely to promote cancers as a result of RET activation." (PMID 28680400, 2017). "The upregulation of GDNF and RET ligand-receptor interaction might participate in glucose-induced cancer progression." (PMID 24864247, 2014). "A single 4 Gy dose of radiation to the DRG alone, cultured with non-radiated cancer cells, significantly inhibited PNI and was associated with decreased GDNF secretion but intact DRG viability." (PMID 22768171, 2012). "In a murine model of PNI, a single 8 Gy dose of radiation to the sciatic nerve prior to implantation of non-radiated cancer cells resulted in decreased GDNF expression, decreased PNI by imaging and histology, and preservation of sciatic nerve motor function." (PMID 22768171, 2012). "In PDAC, neurogenesis is a novel studied biological phenomenon since cancer cells may induce nerve growth and innervation through multiple mechanisms, including secretion of neurotrophic factors such as NGF, BDNF, and the glial cell-derived neurotrophic factor (GDNF)." (PMID 40806192, 2025). "Within tumors, nerve cells release several neurotrophic factors that can modulate the proliferation and phenotype of cancer cells, including Nerve Growth Factor (NGF), Neurotrophins (NT), Brain-Derived Neurotrophic Factor (BDNF) or Glial Cell Line-Derived Neurotrophic Factor (GDNF)." (PMID 38375479, 2024). "Once GDNF/GFRA1/RET makes a complex, it activates various signaling pathways, such as RAS/MAPK, PI3K/Akt and PLCγ pathway, which contribute to cell proliferation, adhesion, migration, differentiation and survival and which contribute to the pathogenesis of both cancer and neuronal disease." (PMID 29617307, 2018). "Our group and others have recently demonstrated that PNI may be facilitated by neural secretion of GDNF, which phosphorylates the RET tyrosine kinase receptor when coupled with the GFRα receptor and triggers downstream signaling pathways that promote cancer cell migration and invasion." (PMID 22768171, 2012). "In addition, we demonstrated that EGF show different functionality than NGF or GDNF and that EGF is a new potential analgesic modulator in the process of pain sensitization, a result of importance not least in the light of the increased use EGFR blockers for therapeutic cancer treatment." (PMID 21187008, 2010). "Cancer cells actively produce and secrete neurotrophic factors, notably nerve growth factor (NGF), brain-derived neurotrophic factor (BDNF), neurotrophin-3 (NT-3), and glial cell line-derived neurotrophic factor (GDNF)." (PMID 41009819, 2025).
cancer (continued). "Although chemokines and neurotrophic factors with chemoattractive properties such as NGF, GDNF, artemin, or neurturin have long been studied in the context of NI in PDAC, the cytoskeletal adaptations of cancer cells during their nerve-directed migration have not been in the focus." (PMID 37607005, 2023).
neurodegenerative disease (62 papers, 2010 to 2025). A disorder of the central nervous system characterized by gradual and progressive loss of neural tissue and neurologic function. "This suggests that very likely, APP and GDNF are linked in different neurodegenerative diseases but the mechanistic aspects are peculiar to the specific disease and still need to be decipher." (PMID 29899726, 2018). "This GDNF activity can be useful in the treatment of neuronal degeneration and loss of differentiation typical for a number of neurodegenerative diseases." (PMID 27286696, 2016). "Beyond its role in development, GDNF exerts a significant neuroprotective role in different pathophysiological conditions, including neuroinflammatory and neurodegenerative diseases, but also some psychiatric disorders and addiction." (PMID 40642294, 2025). "GDNF is known to have neuroprotective effects on dopaminergic neurons in PD and has been studied as a potential therapeutic target for neurodegenerative diseases." (PMID 38891863, 2024). "Similar findings have been reported in observations on the use of GDNF in neurodegenerative diseases where there is low expression of GDNF with a resulting bad neuroprotection extended by oxidative stress." (PMID 39502974, 2024). "Glial cell-line derived neurotrophic factor (GDNF) was proposed to play a role in neurodegenerative disease especially damage of cholinergic CNS neurons like AD." (PMID 39035166, 2024). "This method helped develop a new drug delivery system for treating neurodegenerative diseases by exposing macrophages to plasmid DNA (pDNA) with therapeutic proteins such as catalase or glial cell line-derived neurotrophic factor (GDNF)." (PMID 38699435, 2024). "Deficiency of neurotrophic factors, such as cerebral dopamine neurotrophic factor (CDNF), neurturin and glial cell line-derived neurotrophic factor (GDNF) has also been related to neurodegenerative diseases." (PMID 35425456, 2022). "Accordingly, BDNF and GDNF have been identified as potential therapeutic targets in neurodegenerative diseases, and pre-clinical studies have reported the beneficial effects of the administration of BDNF and GDNF in PD models." (PMID 35204164, 2022). "VEGF and GDNF have known neuroprotective properties and are widely used in gene therapy studies of neurodegenerative diseases, neurotrauma, and stroke." (PMID 36297644, 2022). "Many previous studies have demonstrated that expression-level changes in specific NTFs, such as BDNF, CNTF, and glial cell line-derived neurotrophic factor (GDNF), are associated with the pathogenesis of neurodegenerative diseases, such as AD, PD, HD, and ALS." (PMID 33802760, 2021). "Some NTFs such as BDNF, CNTF, and GDNF are promising candidates for future treatment as they affect the glial activation status and have a beneficial effect on the outcomes of neurodegenerative diseases." (PMID 33802760, 2021). "The search for small molecules based on GDNF and able pass the blood-brain barrier and analysis of their neurotrophic potential for clinical use in neurodegenerative diseases are to be continued." (PMID 34634077, 2021). "Unfortunately, GDNF expression and signaling are dysregulated in neurodegenerative diseases, including PD." (PMID 34769132, 2021). "Numerous experimental studies have revealed that GDNF has pronounced neuroprotective properties, including its ability to protect nervous tissue under hypoxic states and in neurodegenerative diseases." (PMID 31827666, 2019). "Thanks to its robust role in the neuron, GDNF is regarded as a highly promising therapeutic agent for the treatment of neurodegenerative disease." (PMID 29617307, 2018). "GDNF is increasingly recognized to be a potent neurotrophic factor with therapeutic potential against neurodegenerative diseases, including AD." (PMID 26852117, 2016). "Neurotrophic factors, such as glial cell line-derived neurotrophic factor (GDNF), are promising therapeutic agents for neurodegenerative diseases." (PMID 23300823, 2012).